SMC3 (structural maintenance of chromosomes 3)
Diseases named in the same sentence as SMC3 in open-access papers (continued):
Sharing a sentence is not in itself a finding about the gene and the disease.
colon carcinoma (6 papers, 2005 to 2023). "The mRNA levels of SMC3 are elevated in approximately 70% of colon cancer samples, and overexpression of SMC3 promotes fibroblast transformation." (PMID 38017479, 2023). "In several pathological human tissues including colon carcinoma and liver metastatic cancer cells high transcript levels of SMC3 were reported." (PMID 23776448, 2013). "SMC3 expression is elevated in a large fraction of human colon carcinoma and in the intestinal tumors of mice genetically prone to develop polyps." (PMID 16156898, 2005). "SMC3 is frequently elevated in human colon carcinoma and overexpression of the protein transforms murine NIH3T3 fibroblasts." (PMID 16156898, 2005). "SMC3 expression level is controlled in intestinal epithelial cells through the APC/β-catenin/TCF4 transactivation pathway a signaling system that is almost invariably altered in colon carcinomas." (PMID 16156898, 2005).
breast carcinoma (5 papers, 2012 to 2021). "Among them were several nuclear proteins, which have previously been identified in BRCA1-deficient breast carcinomas (TOP1, SMC3, SSRP1 and DHX9)." (PMID 27566577, 2016). "We next sorted the RNASeq data of primary breast cancer patients based on RESTlow and RESThigh groups with 300 patients for each group and examined the expression patterns of TBP, CEBPB, REST, CTCF, RAD21 and SMC3 in addition to unsorted patient dataset." (PMID 30335837, 2018). "In order to determine whether cohesin and Mediator are both required for estrogen-regulated transcription, we performed siRNA-mediated knockdown studies of both SMC3 and MED12 in MCF7 breast cancer cells." (PMID 22913342, 2012).
Anxiety (4 papers, 2017 to 2023). Intense feelings of nervousness, tension, or panic often arise in response to interpersonal stresses. "Mice heterozygous for SMC3 developed abnormal brain architecture, and increased anxiety-related behavior, while complete deletion of SMC3 in neurons resulted in growth restriction and early death." (PMID 35456389, 2022). "Neuron-specific heterozygous Smc3-knockout mice (tau-Cre; Smc3+/flox mice) also showed increased anxiety-like behavior in a novelty-induced hypophagia test." (PMID 28408410, 2017). "Some anxiety-related behavior tests suggest increased anxiety in Smc3+/− mice, whereas other tests, such as the elevated plus maze, did not indicate increased anxiety." (PMID 28408410, 2017). "Previous study on Smc3 cKO mice also exhibited more anxiety-related behavior." (PMID 35379308, 2022). "Smc3+/− mice also exhibited more anxiety-related behavior, which is a symptom of CdLS." (PMID 28408410, 2017). "We further investigated whether decreased expression of neuronal Smc3 produced anxiety-like behavior." (PMID 28408410, 2017). "Indeed, it has been reported that in mice heterozygous for a knockout of SMC3, which encodes the SMC1A partner and the core subunit of cohesin, altered neural gene expression during cortical synapse formation leads to defective synapse development and anxiety-related behavior." (PMID 37107610, 2023).
prostate carcinoma (4 papers, 2022 to 2024). A carcinoma that arises from epithelial cells of the prostate gland. "The results indicated that knockdown of SMC3 sensitized prostate cancer cells to three PARPi drugs." (PMID 36523978, 2022).
developmental delay (3 papers, 2020 to 2024). "Line mutations in several KATs and KDACs, such as KAT6A, SMC3 (coding chromosome protein 3), and HDAC8 (coding histone deacetylase 8, SMC3 deacetylase), are related to developmental retardation, abnormalities, and mental disabilities." (PMID 32399051, 2020). "Previously, a proband with mild facial features and cognitive delay was identified with a de novo 3‐nucleotide (nt) deletion (c.1464_1466del) in SMC3 from a screening of 115 NIPBL‐mutation‐negative individuals with CdLS or CdLS variant phenotypes." (PMID 38733165, 2024).
glioblastoma (3 papers, 2019 to 2021). The most malignant astrocytic tumor (WHO grade IV).
glioma (3 papers, 2021 to 2024). A benign or malignant brain and spinal cord tumor that arises from glial cells (astrocytes, oligodendrocytes, ependymal cells). "In terms of prognostic analysis, consistent with our previous results, high expression of CDK4, HMGB2, and WEE1 could lead to poor prognosis of glioma; however, gliomas with high expression of SMC3 and GADD45G were linked to longer survival." (PMID 34123852, 2021). "Additionally, five DDRGs (CDK4、HMGB2、WEE1、SMC3 and GADD45G) were selected to construct a DDRGs signature for glioma, stratifying patients into low- and high-risk groups." (PMID 34123852, 2021). "The forest map of Cox regression analysis indicated that SMC3 and GADD45G were positively correlated with the prognosis of patients with glioma, whereas CDK4, WEE1, and HMGB2 were negatively correlated with prognosis." (PMID 34123852, 2021). "The DDRGs signature composed of CDK4, HMBG2, WEE1, SMC3 and GADD45G could accurately predict the prognosis of gliomas." (PMID 34123852, 2021).
liver cancer (3 papers, 2018 to 2024). An epithelial or non-epithelial malignant neoplasm that arises from the liver. "The SNV top-ranked SMC3 TFBS motif downstream of FSHR provides a similar example of a previously unknown recurrently mutated TFBS with three liver cancer mutations and three additional SNVs located just outside the element (Fig. 2a14)." (PMID 29354286, 2018).
atopic asthma (2 papers, 2015). An asthma that is characterized by symptoms that are triggered by an allergic reaction caused by inhaled allergens such as dust mite allergen, pet dander, pollen and mold. "SMC3 and RAD21 interact with MXI1 (found among ChIP targets with decreased mRNA) to function in the cohesin complex, and the former is associated with atopic asthma." (PMID 26544975, 2015).
bladder cancer (2 papers, 2012 to 2017). "The chondroitin sulfate proteoglycan 6, also known as structural maintenance of chromosomes 3 (SMC3), has also been found overexpressed in bladder cancer." (PMID 29207682, 2017). "Three SNPs in three genes (FBXO5, SMC3 and SPC24) were associated with significant protective effect on bladder cancer (Ptrend<0.05)." (PMID 22238607, 2012).
ciliopathies (2 papers, 2013 to 2025). "CC2D2A- and TMEM67-associated ID disorders are ciliopathies, and apart from its established role in chromosome cohesion, SMC3 has been recently shown to be required for Planar Cell Polarity, a process underlying cilium formation." (PMID 24204314, 2013). "This study suggests a significant influence of cohesin subunit Smc3 in ciliary structure and function and provides a preliminary link between cohesinopathy and ciliopathy etiologies." (PMID 41263044, 2025).
Cognitive impairment (2 papers, 2024 to 2025). Abnormal cognition is characterized by deficits in thinking, reasoning, or remembering. "The cognitive impairment observed is generally more severe than in patients with mutations in the SMC1A, SMC3, BRD4, and RAD21 genes." (PMID 38673696, 2024).
congenital heart disease (2 papers, 2024). A heart disease that is present at birth. "Our investigation revealed that CdLS patients with SMC3 mutations have high rates of congenital heart disease (CHD)." (PMID 39085358, 2024). "Researchers found that mice without SMC3 had various heart defects, like those seen in humans with congenital heart disease." (PMID 39085358, 2024).
neuroblastoma (2 papers, 2018 to 2022). Neuroblastoma (NB) is the most common solid, extracranial childhood tumor. "Since TH34 treatment induces hyperacetylation of SMC3 in high-grade neuroblastoma cells by blocking HDAC8, we investigated if nuclear morphology and abundance of intact and aberrant mitotic figures changed under TH34 treatment." (PMID 29947893, 2018).
Alzheimer disease (1 paper, 2016). A progressive, neurodegenerative disease characterized by loss of function and death of nerve cells in several areas of the brain leading to loss of cognitive function such as memory and language. "We found genes that are related to cancer (NBN, FAM84B), Huntington's disease (DCTN4), Parkinson's disease (NUCKS1), Alzheimer's disease (SMC3), amongst others." (PMID 27257970, 2016).
cervical carcinoma (1 paper, 2016). A carcinoma arising from either the exocervical squamous epithelium or the endocervical glandular epithelium. "In the correlation network among RAD21, SMC3, and MXI1, the three factors were tightly connected with one another in HeLa-S3 cervical carcinoma cells." (PMID 27139377, 2016).
cleft palate (1 paper, 2024). Cleft palate is a fissure type embryopathy that affects the soft and hard palate to varying degrees. "Cardiac defects were found in a small percentage of SMC1A (15%) and SMC3 (19%) cases, with a small percentage also having cleft palates (3–8%)." (PMID 38673696, 2024).
COVID-19 (1 paper, 2024). A disease caused by infection with severe acute respiratory syndrome coronavirus 2. "In accordance with the PPI analyses, we found that the V-ATPase subunit ATP6V1B2, the c-MYC co-activator TRRAP, and the cohesin complex subunit SMC3 were associated with the COVID-19 patient hospitalization, suggesting their clinical relevance to disease." (PMID 38168026, 2024).
cyst (1 paper, 2024). A sac-like closed membranous structure that may be empty or contain fluid or amorphous material. "RAD21, SMC3, and MEI2 are linked to bloom-promoting sex, HOP2 and MSH4 to cyst germination, while SPO11, MND1, and DMC1 are common to both cyst-forming and non-encysting sex." (PMID 39367346, 2024).
cystic fibrosis (1 paper, 2017). Autosomal recessive disorder caused by pathogenic variants in the CFTR gene (cystic fibrosis transmembrane conductance regulator), which encodes a chloride and bicarbonate channel expressed in epithelial cells, and follow the diagnosis criteria. "Each of the phylogroups Smc1 to Smc4 currently holds ecologically coherent groups of strains: Smc1 and Smc2 contain exclusively Mexican river isolates recovered in this study, Smc3 groups cystic fibrosis isolates and Smc4 predominately rhizosphere isolates from diverse plants and parts of the world." (PMID 28861062, 2017).
diffuse large B-cell lymphoma (1 paper, 2021). "Strikingly, the presence of the Smc3 haploinsufficient GC B-cell transcriptional signature in human patients with GC-derived diffuse large B-cell lymphoma (DLBCL) was linked to inferior clinical outcome and low expression of cohesin core subunits." (PMID 34621263, 2021).
Fanconi anemia (1 paper, 2021). Fanconi anemia (FA) is a hereditary DNA repair disorder characterized by progressive pancytopenia with bone marrow failure, variable congenital malformations and predisposition to develop hematological or solid tumors. "Protein interaction analysis indicates that this “genic signature” (Dclre1a, Rev1, Xpa, Pms2, Brca2, Parp2, Smc3, Nbn, Bax) is mainly involved in the Fanconi anemia pathway and homologous recombination repair." (PMID 34573315, 2021).
female infertility (1 paper, 2021). Diminished or absent ability of a female to achieve conception. "Based on female infertility with both Gdf9-iCre and Zp3-Cre drivers and by scoring the number of follicles in ovaries, we investigated whether loss of Smc3 impacts ovarian reserve." (PMID 34935904, 2021).
heart failure (1 paper, 2024). Inability of the heart to pump blood at an adequate rate to meet tissue metabolic requirements. "In the present study, we elucidated that high Ets2 expression in the heart is regulated by Ets2-SE and SMC3, providing potential insights for precision therapy of heart failure patients." (PMID 39085358, 2024).
Infertility (1 paper, 2021). "We report that depletion of SMC3 in mouse oocytes causes infertility as a result of failed embryogenesis." (PMID 34935904, 2021). "We discovered that, although depletion of Smc3 following meiotic S phase in mouse oocytes allowed accurate meiotic chromosome segregation, adult females were infertile." (PMID 34935904, 2021). "Our findings strongly suggest that depletion of maternal SMC3 in oocytes causes infertility by impacting embryogenesis rather than oogenesis." (PMID 34935904, 2021).
liver fibrosis (1 paper, 2025). "Specifically, THBS1 stands out as a particularly significant gene in this network, with its regulation by both SMC3 and BHLHE40 highlighting its central role in the progression of liver fibrosis and T2DM." (PMID 40299397, 2025).
lymph node tumors (1 paper, 2021). "In order to explore whether these changes in gene expression or other aspects of the malignant phenotype might be linked to 3D architectural effects, we performed in situ Hi-C in lymphoma cells collected from involved mesenteric lymph node tumors of moribund Bcl6 (n=3) and Smc3/Bcl6 (n=3) mice." (PMID 34621263, 2021).
lymphoma (1 paper, 2021). A malignant (clonal) proliferation of B- lymphocytes or T- lymphocytes which involves the lymph nodes, bone marrow and/or extranodal sites. "Strikingly, this reduction in Tet2 promoter to enhancer looping was associated with reduced abundance of Tet2 mRNA in Smc3/Bcl6 vs Bcl6 lymphomas from qPCR experiments performed in independent lymphoma specimens." (PMID 34621263, 2021). "More critically and consistent with the observed aggressive tumor phenotype, Smc3/Bcl6 lymphomas featured induction of canonical GC-associated MYC target gene sets." (PMID 34621263, 2021). "Curiously, although Smc3 behaves as a haploinsufficient tumor suppressor in GC B-cells, it is rarely if ever affected by somatic mutations in patients with GC-derived lymphomas." (PMID 34621263, 2021). "Even though somatic mutations of core cohesin genes in GC derived lymphomas are exceptionally rare, it was previously shown that Smc3 could still function as a tumor suppressor in these cells." (PMID 34621263, 2021). "On the other hand, Smc3 haploinsufficient lymphomas did manifest transcriptional and architectural perturbations consistent with those observed in Smc3 haploinsufficient centrocytes." (PMID 34621263, 2021). "Focusing instead on differential chromatin interactivity, we found a significant bias towards reduction in chromatin loop strength in Smc3/Bcl6 vs Bcl6 lymphomas." (PMID 34621263, 2021). "Yet SMC3 dosage may still be relevant to human GC derived lymphomas since it was shown that patients with low SMC3 expression experience inferior clinical outcomes." (PMID 34621263, 2021). "Taken together with our transcriptional profiling showing enrichment for Tet2 and Kmt2d deficient signatures, these data suggest that reduced levels of Smc3 in lymphomas impairs expression and functionality of tumor suppressor genes through disruption of enhancer-promoter interactions." (PMID 34621263, 2021). "The enrichment of Smc3wt/– centrocyte transcriptional signature in accelerated lymphomas induced by Smc3 haploinsufficiency, prompted us to explore whether these profiles are linked to clinical outcome DLBCL patients." (PMID 34621263, 2021). "Therefore, to gain insight into how SMC3 dosage might contribute to malignant lymphoma phenotypes we explored its transcriptional, architectural and genomic effects in murine B-cell and lymphoma models with Smc3 haploinsufficiency, with correlations to human DLBCL patients." (PMID 34621263, 2021). "Collectively, the data suggest that Smc3 functions as a bona fide tumor suppressor for lymphomas through non-genetic mechanisms, and drives disease by disrupting the commitment of GC B-cells to the plasma cell fate." (PMID 34621263, 2021). "In spite of this, we did not observe increased abundance of DNA damage in Smc3 haploinsufficient murine lymphomas." (PMID 34621263, 2021).
metastatic disease (1 paper, 2024). "In conclusion, the presented work identified the seven genes EMILIN3, MTA1, SV2B, TMPRSS6, ACVR1C, NFAT5 and SMC3 associated with the formation of colorectal BM during the course of disease but not with liver metastasis or non-metastatic disease." (PMID 38558282, 2024).
microcephaly (1 paper, 2014). A congenital or acquired developmental disorder in which the circumference of the head is smaller than normal for the person's age and sex. "One mosaic SMC3 mutation was found in a female individual with severe microcephaly and an atypical facial appearance." (PMID 25125236, 2014).
parasitemia (1 paper, 2023). "Growth curve analysis showed the SMC3 depletion did not significantly affect parasitemia over 5 days of culture." (PMID 37592911, 2023).
polycystic ovary syndrome (1 paper, 2020). A disorder that manifests as multiple cysts on the ovaries. "SMC3 promotes oocyte apoptosis and affects the pathogenesis of polycystic ovary syndrome." (PMID 32825655, 2020).
prion disease (1 paper, 2023). A transmissible disease that is caused by a protein that is able to induce abnormal folding of normal cellular proteins, leading to characteristic spongiform brain changes, which are associated with neuronal loss without an inflammatory response. "Among genes associated with prion diseases, the over-expression of some (PSEN1, FYN, SMC3, CHD2, EP300) in late-cycle could be rationalized by considering related proteins in humans, which, when expressed in their monomeric (soluble) form, exert protective functions for cellular homeostasis." (PMID 37048113, 2023).
Roberts syndrome (1 paper, 2021). "Additionally, mutations in three Cohesin subunits (SMC1α, SMC3, RAD21) and in one Cohesin-interacting protein (NIPBL) have been found causal for CdLS, whereas mutations in ESCO2 are responsible for Roberts syndrome/SC Phocomelia (OMIM# 269000)." (PMID 33263776, 2021).